RRM2 (ribonucleotide reductase regulatory subunit M2)
Diseases named in the same sentence as RRM2 in open-access papers (continued):
Sharing a sentence is not in itself a finding about the gene and the disease.
cancer (continued). "Uncontrolled proliferation of cancer cells must be supported by a sufficient dNTP supply, and is reflected by RRM2 overexpression in various types of cancers." (PMID 31324785, 2019). "The expression of three RR genes, especially RRM1 and RRM2, increased significantly across common types of cancers." (PMID 31637211, 2019). "Using the Spearman's correlation coefficient analysis, the consistent positive correlations were observed between RRM1 and RRM2 expression in all 31 types of cancer." (PMID 31637211, 2019). "RRM2 is important in controlling cellular function in a number of human malignant tumors, including DNA repair, cell proliferation and senescence." (PMID 30778371, 2019). "If RRM2 gene therapy combined with chemotherapy is an effective method for increasing the sensitivity of resistant cancer cells to chemotherapeutic agents, it will efficiently reduce the recurrence of invasion and migration." (PMID 31673243, 2019). "Altogether, our data show that EZH2 cooperates with E2F1 to stimulate expression of genes involved in ACC aggressiveness and establishes RRM2 as an interesting therapeutic target in this cancer." (PMID 31363169, 2019). "To further study associations of RRM1, RRM2, and RRM2B expression in different cancer types and TNM stages, we downloaded and analyzed the RNA-seq and clinicopathologic data of 31 types of cancer from TCGA." (PMID 31637211, 2019). "Among these, only four genes were significantly downregulated in fibroblasts compared with cancer cells (Nt5c1A, Nt5c3, Rrm2 and Ent2)." (PMID 28077438, 2018). "Because both dTMP and deoxyribonucleotides are necessary for DNA replication and repair, inhibition of TYMS and RRM2 has been suggested to induce apoptosis in cancer cells." (PMID 28407751, 2017). "Numerous small molecule inhibitors, such as hydroxyurea (HU), gemcitabine (both approved for human cancer clinical use) and triapine, interact with the RRM2 subunit and inhibit RR activity." (PMID 26675256, 2016). "One of the major targets of gemcitabine is RRM1 and RRM2, which ensure sufficient supply of dNTP pool for DNA synthesis of proliferating cancer cells." (PMID 26894857, 2016). "TOP2A (DNA topoisomerase 2-α) and RRM2 (ribonucleoside-diphosphate reductase subunit M2) are noteworthy examples of proteins with both a well-established role in cancer development and prognostic value." (PMID 26527623, 2016). "In some cancers, a high level of RRM2 mRNA correlates with chemotherapeutic resistance, cellular invasiveness and unsatisfied prognosis, suggesting that RRM2 contributes to malignant progression and is a potential therapeutic target." (PMID 26658059, 2015). "Phase I and II clinical therapeutic trials have been evaluated using siRNAs to inhibit critical cancer-associated genes, including siRNA-EphA2-DOPC (targeting EphA2), TKM-080301 (targeting PLK1), and CALAA-01 (targeting RRM2)." (PMID 26448935, 2015). "The RRM2 mRNA level is inversely correlated with the response rate in cancer patients treated with gemcitabine." (PMID 25946136, 2015). "There was significantly increased expression in cancer compared to normal appearing adjacent bronchial epithelium for both nuclear and cytoplasmic RRM2 (p < 10–5)." (PMID 26001082, 2015). "Our findings showed that the RRM2 immunoreactivity in cancer tissues is higher than that in high-grade dysplasia, low-grade dysplasia and normal tissues of the uterine cervix." (PMID 24637958, 2014). "The RRM2 expression in cancer tissues was higher than that in high-grade dysplasia, low-grade dysplasia or normal cervical tissues." (PMID 24637958, 2014). "Many studies have shown that using small interfering RNA (siRNA) to inhibit RRM2 overexpression significantly reverses cancer cell resistance to chemotherapy agents and gamma radiation." (PMID 25213022, 2014).
cancer (continued). "CALAA-01 consists of siRNA against the M2 subunit of ribonucleotide reductase (RRM2), which is involved in the proliferation of cancer cells, and targeted to cancer cells via a human transferrin protein targeting ligand." (PMID 24472581, 2014). "RRM2 upregulation has been demonstrated to increase cell proliferation and the malignant potential of certain types of cancers, and that inhibition of RRM2 reduced cell proliferation in vitro and in vivo." (PMID 24637958, 2014). "Ribonucleotide Reductase M2 subunit (RRM2), which is expressed when DNA replication occurs, is overexpressed in a number of solid tumors and is an established anti-cancer target." (PMID 24348903, 2013). "A subset of the targets (BCL2, CLU, HSPB1, BIRC5, EIF4E and RRM2) is being investigated for cancers in combination with approved cytotoxic drugs." (PMID 22989709, 2012). "To further confirm the implication of RRM2 in the regulation of TSP-1 and VEGF expression, we measured TSP-1 and VEGF expression level, after RRM2 in cancer cells was knocked down by its specific siRNA." (PMID 19250552, 2009). "We investigated the effect of overexpression of RRM2 on the production of angiogenesis regulatory factors in human cancer cells." (PMID 19250552, 2009). "Pan-cancer analysis demonstrated that RRM2 has universal functions across various malignancies." (PMID 41970950, 2026). "RRM2, a crucial enzyme, is accountable for the vital transformation of ribonucleotides to deoxyribonucleotides, ranking among the highly expressed enzymes identified in cancer." (PMID 40303288, 2025). "Accordingly, vaccinia viruses with inhibited F4L functions may replicate using cell-derived RRM2 in cancer cells where cells are actively proliferating." (PMID 40048445, 2025). "•RRM2 and ADH1B were emerged as robust pan-cancer diagnostic biomarkers." (PMID 39884577, 2025). "We queried bioinformatics databases to evaluate RRM2 expression in 16 human cancers." (PMID 40732324, 2025). "The analysis revealed a substantial down-regulation of let-7c-5p in cancer samples (P = 1.9e-18), hinting that its diminished expression might contribute to the up-regulation of RRM2 and potentially foster tumorigenesis." (PMID 41357570, 2025). "RRM2, upregulated in different cancers, is a critical enzyme in cell proliferation, and has been shown to exert anti-ferroptotic activity in some cancer cells." (PMID 41155419, 2025). "Notably, RRM2 and ADH1B, two genes which belong to PCUGs and PCDGs, respectively, were identified as robust pan-cancer diagnostic biomarkers." (PMID 39884577, 2025). "Strikingly, we identified that RRM2 and ADH1B are upregulated and downregulated, respectively, in all 13 cancer types, suggesting that this pair of genes could serve as promising pan-cancer diagnostic biomarkers." (PMID 39884577, 2025). "A literature review revealed that RRM2 is commonly upregulated in many cancers, including HCC." (PMID 40493217, 2025). "RRM2 overexpression is commonly associated with chemoresistance by enhancing DNA repair and survival signaling; thus, inhibiting RRM2 could sensitize cancer cells to chemotherapy." (PMID 40493217, 2025). "Finally, rescue assays demonstrated that P7C3 exert its anti-cancer effects via regulating RRM2 expression." (PMID 38356717, 2024). "Subsequently, the significance of RRM2 in pan-cancer clinical prognosis was explored." (PMID 38635758, 2024). "Indeed, analysis of alterations in gene expression in different cancer types places RRM2 among the top 10% of the most upregulated genes in 73 of the 168 total cancer types studied." (PMID 39206868, 2024). "Actually, the relationship between cancer and RRM2 was widely reported." (PMID 38820515, 2024).
cancer (continued). "Moreover, cancer cells are reported to have multiple mutations in other regions of hRRM1, as well as in other RNR subunits, RRM2 and RRM2B, that possibly also can negatively impact dNTP pools." (PMID 39360631, 2024). "Additionally, survival analyses using Kaplan–Meier and Cox regression models revealed that most patients with cancer and high RRM2 expression exhibited significantly worse survival rates than those with low expression." (PMID 38635758, 2024). "Previous studies have demonstrated the significant role played by RRM2 in various types of cancer." (PMID 40625451, 2024). "Moreover, RRM2 is an important target of many factors and drugs that suppress tumorigenicity in various cancers." (PMID 38635758, 2024). "The expression levels of RRM2 were extremely different between the cancer and normal groups." (PMID 38635758, 2024). "We also explored the molecular mechanisms of RRM2 in the context of different cancers using a series of factors, including gene expression, clinical correlation, survival analysis, genetic alterations, immune infiltration, immune checkpoints, enrichment analysis, and potential drug prediction." (PMID 38635758, 2024). "Upon entrance into the cancer cells, siRNA inhibited RRM2 expression." (PMID 39482766, 2024). "Recent studies suggested that RRM2 may play an important role as a bridge between senescence and cancer." (PMID 38804044, 2024). "We explored the correlation between RRM2 and immune checkpoint gene expression in various cancers." (PMID 38635758, 2024). "There is also evidence that RRM2 overexpression promotes angiogenesis, whereas its downregulation induces apoptosis and G1-phase arrest, in addition to inhibiting cell proliferation in various cancer types." (PMID 36768940, 2023). "According to various studies, RRM2 can also be used as a target for antilung cancer drugs." (PMID 37137710, 2023). "Combined, these results suggest that RRM2 may serve as a predictor of both cancer clinical outcomes and immunotherapy among a variety of cancers." (PMID 36518297, 2022). "We investigated the relationship between RRM2 expression and pathological stages of cancer." (PMID 36518297, 2022). "Given these limitations, we conducted an integrative bioinformatics analysis of RRM2 in pan-cancer." (PMID 35740608, 2022). "Therefore, RRM2 is a promising target for repurposed anti-cancers as it was found to be overexpressed in our study and probably interact with SARS-CoV-2 proteins." (PMID 35831333, 2022). "To verify the correlation between RRM2 and immune cell infiltration, we tested whether RRM2-expressing cancers exhibited gene expression signatures of high immune infiltration." (PMID 35911380, 2022). "Using GEPIA2, we analyzed the mRNA expression status of RRM2 across numerous cancer types." (PMID 36518297, 2022). "RRM2 expression significantly overexpressed among 28 types of cancer." (PMID 36518297, 2022). "In future updates, we hope that the RRM2 inhibitor could serve as a new combination agent of therapy target in cancers." (PMID 35740608, 2022). "Therefore, in this study, we utilized the TCGA data to establish a comprehensive bioinformatics-based pan-cancer analysis of RRM2." (PMID 36202136, 2022). "This study aimed to elucidate the comprehensive landscape of RRM2 in human cancers." (PMID 35740608, 2022). "In this study, we elucidated the comprehensive landscape of RRM2 in human cancers." (PMID 35740608, 2022). "We provided the prospect of RRM2 and immunotherapy for pan-cancer." (PMID 35740608, 2022). "Then with IHC images from HPA database, we showed protein levels of RRM2 in several cancers." (PMID 35740608, 2022).
cancer (continued). "Additionally, RRM2 inhibitors have been applied to treat solid tumors and blood malignant tumors as a single agent or in combination with other therapies." (PMID 35740608, 2022). "For the first time, we systematically analyzed the role of RRM2 in pan-cancer." (PMID 35740608, 2022). "Ribonucleotide reductase M2 subunit (RRM2), a small subunit of the ribonucleotide reductase complex that acts as an oncogenic role under pathological conditions, and its overexpression was found in various cancers including NSCLCs." (PMID 35444699, 2022). "Above all, RRM2 may be a valuable molecular biomarker for predicting prognosis and immunotherapeutic efficacy in pan-cancer, particularly in LIHC." (PMID 36518297, 2022). "Furthermore, we estimated the immune compartments of cancers, and discovered that RRM2 was correlated with the infiltrating immune cells." (PMID 35740608, 2022). "The expression and role of RRM2 have been reported in a variety of cancers." (PMID 35290409, 2022). "More importantly, we justified that blocking RRM2 with siRNA could significantly suppress BLCA cancer cell growth with CCK-8 and colony assays." (PMID 35740608, 2022). "Increased RRM2 expression may be predictive of a poor overall survival (OS) in patients with seven different cancers." (PMID 36518297, 2022). "The exact mechanism of RRM2 in cancers still needs to be tested in vivo and in vitro." (PMID 35740608, 2022). "We found RRM2 gene was highly expressed in 30 types of cancers." (PMID 36202136, 2022). "Collectively, we found that RRM2 is a novel prognostic biomarker, and these findings may aid in an improved understanding of the role of RRM2 and its clinical application in human cancers." (PMID 35740608, 2022). "In particular, we discovered that RRM2 was correlated with predictors of immunotherapy, which might provide a reference for guiding immunotherapy in cancers." (PMID 35740608, 2022). "The role of RRM2 in response to immunotherapy should be validated in clinical cancer patients." (PMID 35740608, 2022). "Moreover, the composite function of RRM2 cooperating with immune cells, and the molecular mechanisms and detailed pathways of RRM2 in human cancers remain enigmatic." (PMID 35740608, 2022). "Our pan-cancer analysis provides a comprehensive summary of the oncogenic roles of RRM2 in a variety of human cancers, particularly its role in LIHC and the association between RRM2 and a poor prognosis." (PMID 36518297, 2022). "Moreover, we analyzed the relationship of immune checkpoint receptors with RRM2 expression in different types of cancers." (PMID 36202136, 2022). "Consequently, RRM2 overexpression plays a critical part in the proliferation, metastasis and drug dependence of human cancers." (PMID 35740608, 2022). "And we performed a pan-cancer analysis of the genetic alteration status and methylation of RRM2." (PMID 36202136, 2022). "Here, we first investigated RRM2’s expression and survival analysis across multiple cancer types." (PMID 35911380, 2022). "Genetic alterations of RRM2 in pan-cancer samples were analyzed in cBioPortal." (PMID 35740608, 2022). "We identified the genes and signaling pathways regulated by RRM2 during cancer development." (PMID 36518297, 2022). "Therefore, despite the intensive efforts to investigate RRM2 function in cancers before, the brand-new role of RRM2 in ferroptosis and iron homeostasis is still worth pursuing." (PMID 35740608, 2022). "This is the first pan-cancer analysis focusing on the significance of RRM2, to our knowledge." (PMID 36518297, 2022). "RRM2 may be a valuable molecular biomarker for predicting prognosis and immunotherapeutic efficacy in pan-cancer, particularly in LIHC." (PMID 36518297, 2022).
cancer (continued). "Though it has been reported in previous studies that RRM2 activates the AKT pathway in cancer cells, the underlying mechanisms have not been identified." (PMID 34319001, 2021). "Thus, CCNF-triggered RRM2 reduction (in the CCNF-RRM2 axis) likely unleashes anti-cancer mechanisms against BRCA." (PMID 34201347, 2021). "Triapine, a new-generation lipophilic iron chelator, has been identified to be one of the most potent inhibitors of RRM2 and may be a promising therapeutic strategy for cancers as well." (PMID 33380233, 2021). "Namely, FOXM1 promotes epithelial-mesenchymal transition and metastasis formation for breast and various other cancers, RRM2 contributes to poor survival and tamoxifen resistance development, while expression levels of CDK1, PLK1 and RACGAP1 were shown to be prognostic markers." (PMID 33852600, 2021). "Thus, RRM2 can modulate cancer cell proliferation, DNA repair, and apoptosis by regulating replication and transcription." (PMID 34799689, 2021). "Among them, RRM2 has a crucial role in mediating cancer cell survival and progression." (PMID 34567073, 2021). "The high level of RRM2 expression has received extensive attention in several cancers." (PMID 34093788, 2021). "We assumed that combined inhibiting transcription with promoting degradation of RRM2 might more efficiently downregulate the increased RRM2 level in cancer cells." (PMID 34234118, 2021). "For example, in cancer cells with loss of SETD2, a decrease in levels of the RRM2 ribonucleotide reductase subunit can create a vulnerability, which can be exploited by the WEE1 inhibitor adavosertib that further reduce RRM2 levels, leading to S phase arrest as a result of a depleted dNTP pool." (PMID 35069219, 2021). "Therefore, further understanding of the abnormally regulatory mechanisms of RRM2 expression thereby RR activity in cancers is of important significance for cancer treatment." (PMID 34234118, 2021). "In cancers, the increased level of RRM2 is abnormally regulated mainly through transcription and degradation pathways, since there are extremely low copy number variation (CNV) and mutation rates in RRM2 gene." (PMID 34234118, 2021). "However, the detailed abnormally regulatory mechanisms for RRM2 expression in cancers and their implications in cancer treatment are still elusive." (PMID 34234118, 2021). "Finally, to further reveal the importance of RRM2 in other cancers, we evaluated the RRM2 expression pattern in a series of cancer types from the UALCAN database." (PMID 33372599, 2020). "For example, the anti-RRM2 siRNA duplex shows anti-proliferative activity in cancer cells." (PMID 32953265, 2020). "CCNB1, CKS2, MKI67, RRM2, TK1 and TOP2A were found with positive clinical correlation to GLEASON SCORE, and we could clearly identify the core factors as cancer risk factors, the expression level increased as Gleason score elevated." (PMID 32266115, 2020). "Unlike RRM1 and RRM2, p53R2 suppresses invasiveness and its expression is usually associated with a better prognosis for cancer patients." (PMID 31936661, 2020). "For example, an anti-RRM2 siRNA duplex exhibits anti-proliferative activity in cancer cells." (PMID 31936661, 2020). "Functional network analysis suggested that RRM2 regulates RNA transport, oocyte meiosis, spliceosome, ribosome biogenesis in eukaryotes, and cellular senescence signaling through pathways involving multiple cancer-related kinases and E2F family." (PMID 33123291, 2020). "The ribonucleotide reductase small subunit M2 (RRM2) gene plays an oncogenic role in many cancers." (PMID 32385899, 2020). "The six hub genes (BIRC5, TOP2A, FANCI, NCAPG2, RAD51, and RRM2) were reported to be critical to regulate cell cycle, and their abnormal expression could lead to development and progression of cancers." (PMID 32902196, 2020). "RRM2 gene expression and functions in carcinoma have been recently reported." (PMID 33411689, 2020).